CXCR4 (C-X-C motif chemokine receptor 4)
Diseases named in the same sentence as CXCR4 in open-access papers (continued):
Sharing a sentence is not in itself a finding about the gene and the disease.
colon carcinoma (continued). "The protein and mRNA expression levels of SDF-1 and CXCR4 and their downstream proteins cyclin D1 and c-myc in the tumour tissues of mice with colon cancer were detected by Western blot." (PMID 34531745, 2021). "Conversely, colon cancer cells with low CXCR4 levels were resistant to the tested anti-cancer agents, indicating that cancer cell dormancy is associated with drug resistance." (PMID 35582377, 2021). "The expression of CXCR4 in colon cancer cells after treating with stromal cell-derived factor-1α (SDF-1α, or CXCL12) was investigated, along with the cancer cell proliferation rate and chemosensitivity to 5-FU, irinotecan, and oxaliplatin." (PMID 35582377, 2021). "We also found increases in 5hmC in the CXCR4 gene body in an independent cohort of colon tumors, consistent with 5hmC serving as a marker of active gene transcription." (PMID 32110952, 2020). "The aim of the study was to improve the efficacy of colon cancer standard therapy targeting CXCR4 with a new CXCR4 antagonistic peptide by reversing the EMT program." (PMID 32708431, 2020). "Additional studies to discover new or novel genetic and epigenetic mechanisms regulating CXCR4 are warranted to potentially target CXCR4 in colon cancer." (PMID 32110952, 2020). "Taken together, the results showed that targeting CXCR4 ameliorates the effect of treatment in colon cancer through inhibition of cell growth and reversal of EMT treatment-induced markers, supporting further clinical studies." (PMID 32708431, 2020). "In the case of tumor metastasis, CXCL12 is released from stromal cells within the metastatic microenvironment, which in turn activates CXCR4 on cancer cells to increase cancer cell adhesion, motility and invasion in colon cancer cells." (PMID 32110952, 2020). "This is further supported by increased metastatic properties in colon cancer cells following CXCR4 activation and inhibition of these characteristics with anti-CXCR4 antibodies." (PMID 32110952, 2020). "For example, RNA-seq expression profiles from a large sample of colon tumors in TCGA, revealed that CXCR4 mRNA expression in tumors remained stable across tumor stages (I–IV)." (PMID 32110952, 2020). "CXCR4 expression levels were measured using qPCR and immunoblotting in normal colon tissues, primary colon cancer tissues and CRC cell lines." (PMID 32110952, 2020). "The chemokine receptor CXCR4 is overexpressed in colon cancer, where it represents a poor prognostic factor." (PMID 32708431, 2020). "The methylation status in the CXCR4 gene body was analyzed using previously performed nano-hmC-seal data from colon cancers and adjacent normal colonic mucosa." (PMID 32110952, 2020). "In this study, we demonstrated that stromal cell-derived CXCL12 induced the suppression of expressed PTEN and enhanced both proliferation and invasion through the activated CXCL12/CXCR4/PI3K/Akt signaling pathway in colon cancer cells." (PMID 31500630, 2019). "Expectedly, the percentage of CD8+ T-cells were significantly reduced in CXCR4+/−Apcmin/+ mice compared with Apcmin/+ mice in colonic cancer tissues by IHC staining." (PMID 30678736, 2019). "The expression of PTEN, CXCL12 and CXCR4 mRNA and protein were detected in colon cancer cell lines and stromal cells using RT-PCR and Western blot." (PMID 31500630, 2019). "MCF7 and HT-29 (a colon cancer cell line) expressed similar levels of CXCR4, but only MCF7 expressed higher levels of CXCR7, which correlated with enhanced cell growth advantage in response to stromal cell CM." (PMID 30993013, 2019). "Most recently, ALDH1A3 was shown to affect colon cancer in vitro proliferation and invasion depending on CXCR4 status." (PMID 30087899, 2018). "Western blot showed that CXCL12 protein was only expressed in DLD-1 cells, and CXCR4 was expressed in four colon cancer cell lines." (PMID 29305742, 2018). "CXCL12 mRNA was expressed only in DLD-1 colon cancer cell line, while CXCR4 mRNA was expressed in four colon cancer cell lines." (PMID 29305742, 2018).
colon carcinoma (continued). "We report that human cathelicidin antimicrobial peptide, LL-37, and its analogues suppress the proliferation of colon cancer cells via the upregulation of miR-663a abrogating CXCR4 expression." (PMID 28061765, 2017). "C-X-C chemokine receptor type 4 (CXCR4) is broadly expressed in various malignant tumors including colon cancer." (PMID 28061765, 2017). "For this, expression of CXCR4 on HT-29 cells, a colon cancer cell line, was confirmed by flow cytometry, where ~ 36% of the cells appeared to be CXCR4-positive, with little fluctuation over time." (PMID 28945785, 2017). "Consistent with the results of the present study, CXCR4 (C-X-C motif chemokine receptor 4) is highly expressed in metastatic colon cancer in the liver compared with primary colon cancer tissue, and elevated CXCR4 expression levels contribute to poor survival." (PMID 28629469, 2017). "We next analyzed the relationships between the levels of CXCR4, components of the RhoA signaling and clinicopathologic characteristics of colon cancer patients." (PMID 27517626, 2016). "If CXCR4 indeed is a functional target of miR-126 in colon cancer cells, reintroduction of CXCR4 into miR-126 overexpressing HCT116 cells and inhibition of CXCR4 in miR-126-silenced SW480 cells should antagonize the effects of miR-126 on its target genes." (PMID 27517626, 2016). "Inhibition of CXCR4 in colon cancer cells has been recently shown to suppress interaction with these ligands and thus reduce metastasis formation." (PMID 27835905, 2016). "Collectively, these results demonstrated that miR-126 acts as a tumor suppressor by inactivating RhoA signaling via CXCR4 in colon cancer." (PMID 27517626, 2016). "Accordingly, our results showed that CXCR4 can reverse the effects of miR-126 on RhoA signaling pathway in colon cancer." (PMID 27517626, 2016). "In this study, we present evidence that reduction in miR-126 expression, up-regulation of CXCR4 and components of the RhoA signaling pathway in colon cancer tissues were significantly correlated with TNM stages, lymph node metastasis and poor clinical outcome." (PMID 27517626, 2016). "Based on our previous studies, we used tissue microarrays to show that CXCR4 and components of the RhoA signaling pathway were up-regulated in colon cancer tissue compared with those in adjacent normal mucosa tissues." (PMID 27517626, 2016). "Taken together, our findings suggested that miR-126 acts as a tumor suppressor by inactivating the RhoA signaling pathway via CXCR4 in colon cancer." (PMID 27517626, 2016). "There was a significant accumulation of CXCR4-expressing MDSCs around colonic tumours (50- to 100-fold), along with increased expression of pro-tumorigenic cytokines IL-17A and IL-1β, in Tff2-null and wild-type mice compared with CD2–Tff2 mice." (PMID 26841680, 2016). "Functional assays showed that transfection with the CXCR4 plasmids in miR-126 overexpressing HCT116 cells significantly ameliorated the miR-126-induced suppression of colon cancer cell migration, invasion and proliferation, respectively." (PMID 27517626, 2016). "Accordingly, our results revealed that miR-126 down-regulated the expression of CXCR4 and the critical components involved in RhoA signaling pathway in human colon cancer cells." (PMID 27517626, 2016). "In vivo and in vitro, miR-126 suppressed the invasion and migration of the colon cancer cells by down-regulating CXCR4 and inactivating the RhoA signaling pathway." (PMID 27517626, 2016). "In human colon carcinomas, we observed that CXCR4 expression significantly increased during tumor progression as it increased from stages 0-II to III-IV, whereas for CXCR7, a significant increase was observed between early stages and liver metastases." (PMID 24629239, 2014). "CXCR4 expression is a prognostic marker in various types of cancer, including acute myelogenous leukemia, breast and colon carcinomas." (PMID 23497377, 2013).
colon carcinoma (continued). "Additional studies suggest that CXCR3 activation in colon cancer synergistically enhances CXCR4-mediated tumor cell migration to the lymph nodes, liver, and lungs." (PMID 24259307, 2013). "We used nude mice hepatic metastasis assays to examine the effect of blocking CXCR4 with AMD3100 on hepatic metastasis of colon cancer." (PMID 22871210, 2012). "In this study, we have provided evidence for the existence of a distinct migrating CSC subpopulation of CD133+CXCR4+ cells in human CRC specimens as well as in the human colon cancer cell line, HCT116." (PMID 22871210, 2012). "A high CD133+CXCR4+ cell content was significantly correlated with rectal tumors when compared with colon cancer (P = 0.02), high TNM stages (P = 0.02), and distant metastases as indicated by M status (P = 0.03)." (PMID 22871210, 2012). "We also found that high expression of HIF-1α, CXCR4, and VEGF is associated with increased metastatic potential in human colon cancer." (PMID 20953377, 2010). "We therefore concluded that neutralizing antibodies to CCL20 suppressed in vivo CXCR4-dependent and independent prostate and colon tumor growth." (PMID 19340288, 2009). "Additionally, CXCR7, a receptor related to CXCR4 and CXCL12, has been associated with the growth and metastasis of tumor cells in colon cancer, melanoma, and BCa." (PMID 39070795, 2024). "Besides, CXCL12-KDEL retention protein was used to block colon cancer cells, resulting in repression of the signaling involved in CXCR4 and a significant reduction in the metastatic cancer growth." (PMID 35388021, 2022). "Likewise, reduction of CXCR4 expression by siRNA in human colonic tumor cells cultured in hypoxia decreases CXCL12-induced phosphorylation and activation of Akt, while ERK activation is unchanged." (PMID 35406582, 2022). "CXCR4 is a target for miR-126-mediated repression, and this repression may inhibit migration and invasion of colon cancer cells." (PMID 33953222, 2021). "Furthermore, suppression of CXCR4 led to down-regulation of invasion induced by the C-X-C chemokine ligand 12 (CXCL12) ligand in HCT116 colon cancer cells." (PMID 33801741, 2021). "The presence of CXCR7/CXCR4 heterodimers was detected in 65% of colon cancers by confocal imaging." (PMID 34298991, 2021). "However, we observed selective involvement of CXCR4 in significantly modulating paclitaxel resistance in breast and colon cancers, which is actually in corollary with vast literature documenting the pro-tumorigenic role of CXCR4." (PMID 33966046, 2021). "A high CXCR4 expression in cancer cells may be an independent predictor of lymph node metastases and poor survival in colon cancer patients." (PMID 34298657, 2021). "The toxin targeted CXCR4+ colon cancer cells specifically and induced pyroptosis." (PMID 33718226, 2021). "It should be noted that our findings show that CT-26 cells also express CXCR4, which could therefore be involved in the peritoneal dissemination of colon cancer cells and deserves to be examined in future studies." (PMID 34115261, 2021). "In this study, we provide evidence that CXCL12/CXCR4/PI3K/Akt cascade may be critical for colon cancer cells to metastasize." (PMID 31500630, 2019). "CXCR4 is also found to be overexpressed in the majority of colon cancer cases." (PMID 30197752, 2018). "However, whilst SW480 (human colon cancer) cells do express CXCR4, their expression of CCR7 is negligible." (PMID 28432337, 2017). "In our studies, we demonstrated that restoration of CXCR4 could significantly reverse the effect of miR-126 on the migration, proliferation and invasion of colon cancer cells, and abolish the effects of miR-126 on RhoA signaling." (PMID 27517626, 2016). "Consistent with the findings of colon cancer tissue microarray, we also found that miR-126 significantly suppressed the expression of CXCR4, the activity of RhoA, and the expression of RhoGEF, ROCK, PI3K, PAK, PKN and up-regulated the expression of ARHGAP5 in colon cancer cells." (PMID 27517626, 2016).
colon carcinoma (continued). "Moreover, blocking CXCR4 expression on the cell surface greatly inhibited the ability of colon cancer cells to metastasize to organs." (PMID 27668882, 2016). "Our previous study also provided evidence for the existence of a distinct migrating CSC subpopulation of CD133 + CXCR4+ cells in the human colon cancer cells and demonstrated that CD133 + CXCR4+ cancer cells were possible migratory CSC subtypes in colon cancer." (PMID 26864651, 2016). "Platelet activation with a PAR1 agonist triggered TGF-β secretion, which induced EMT of SW620 human colon cancer cells via the downregulation of miR-200b expression, and activated platelets had a chemotactic effect on colon cancer cells mediated by the upregulation of CXCR4 on the cell surface." (PMID 25846512, 2015). "Others have also shown that CXCR2 and CXCR4 are expressed on the colon cancer cell lines used here." (PMID 24887129, 2014). "Thus, the CXCL12/CXCR4 interaction permits extravasation of colon tumor cells in the liver parenchyma." (PMID 24629239, 2014). "Interestingly, our results indicated that inactivation of Wnt signaling via overexpression of the short form of LEF-1 also down-regulated the expression of CXCR4 in colon cancer cell lines, but CXCR4 expression was enhanced by the full form of LEF-1 in HT29." (PMID 22639890, 2012). "CXCR4 is said to play a key role in tumour progression and metastasis in colon cancer." (PMID 22433494, 2012). "Strategies targeting the SDF-1/CXCR4 interaction may have important clinical applications in the suppression of colon cancer metastasis." (PMID 22871210, 2012). "In our study, a nude mouse hepatic metastasis model was employed, and the results indicated that chemical inhibition of CXCR4 with AMD3100 could inhibit colon cancer metastasis to the liver." (PMID 22871210, 2012). "This might be due to higher CXCR4 expression in rectal cancer than in colon cancer, suggesting that the percentage of CD133+CXCR4+ cancer cells in future studies should be investigated separately in colon and rectal cancer rather than in a mixed way." (PMID 22871210, 2012). "We hypothesized that blockade of the SDF-1/CXCR4 axis might suppress colon cancer metastasis to the liver, with the knowledge that the liver secretes high amounts of SDF-1." (PMID 22871210, 2012). "Therefore, we analyzed the correlation between the high expression of both HIF-1α and CXCR4 and clinicopathologic significance in human colon cancer samples." (PMID 20953377, 2010). "Moreover, overexpression of CCL20 or CXCR4 in prostate and colon cancer cells promotes tumor growth that was neutralized with anti-CCL20 antibodies." (PMID 19340288, 2009). "In a murine model only CXCR4 expressing, but not CXCR4-deficient CT-26 colon carcinoma cells grew into macrometastases; nonetheless both cell types were able to colonise livers and lungs after injection." (PMID 16819541, 2006). "A recent work consolidates the current results by proposing an increased risk of colon cancer liver metastasis caused by the ERK1/2-stimulated upregulation of ANGPT2 and CXCR4, thereby proving a mechanism for how ERK1/2 signaling may promote colon cancer cell invasion." (PMID 38247543, 2024). "Irrespective of CXCR4 surface expression, by utilizing stable gain and loss of function approaches, we observe that intracellular CXCR4 protein selectively resists and sensitizes colon cancer cells against paclitaxel therapy in vitro and in vivo." (PMID 33966046, 2021). "GA has also been shown to activate AMPK in SW480 colon cancer cells and to decrease expression of invasion-associated proteins, including matrix metalloproteinase (MMP)-2, MMP-9, urinary-type plasminogen activator (uPa), and C-X-C chemokine receptor type 4 (CXCR4) in the SW480 cells." (PMID 34681204, 2021).
colon carcinoma (continued). "Interestingly, drug-resistant HT-29 colon carcinoma cells selected after chronic treatment with different drugs (i.e., 5-fluorouracil, methotrexate, doxorubicin or oxaliplatin) also exhibited high expression of CXCR4." (PMID 31557914, 2019). "Besides, our results reveal that DNA methylation could cause CD164 overexpression in the early stage of PTC, and it has been reported that CD164 could promote the proliferation and metastasis of colon cancer cells in vivo and vitro through the CXCR4 pathway." (PMID 31126066, 2019). "CXCL12/CXCR4/PI3K/Akt cascade may be critical for colon cancer cells to metastasize." (PMID 31500630, 2019). "Hence, these data suggest that CAFs induce colon cancer progression via the SDF-1/CXCR4 axis." (PMID 30355650, 2018). "The co-expression of CXCR4 and CD133 in colon cancer may be associated with unfavorable prognosis." (PMID 27314328, 2016). "In addition, either in miR-126-overexpressing or in miR- 126-silenced colon cancer cells, the restoration of CXCR4 could significantly reverse the proliferation and invasion, as well as abolish the effects of miR-126 on RhoA signaling pathway." (PMID 27517626, 2016). "Thus, the function of CXCR3 in colon cancer may depend on its cooperation with other expressed chemokine receptors such as CXCR4 and CCR7." (PMID 24259307, 2013). "Highly expressed in colon cancer, CD164 drives proliferation and metastases along the CXCL12 (SDF-1)/CXCR4 signaling axis." (PMID 40692786, 2025). "Noteworthy examples include the overexpression of CXCR2 in NK cells targeting renal cell carcinoma and the combined overexpression of CXCR4 and CCR7 for colon cancer." (PMID 39339180, 2024). "In colon cancer cell lines, ALDH1A3 knockdown decreased cell proliferation and C-X-C chemokine receptor type 4 (CXCR4) expression, suggesting a potential connection between the two." (PMID 36672441, 2023). "Immunohistochemical analysis confirmed that CXCR4 and AFP levels were increased in liver metastases compared to primary colon tumors." (PMID 36591565, 2022). "Recently, the CD133+/CXCR-4+ populations of cancer stem cells were found to be the possible migratory cells and the co-expression of CXCR-4 and CD133 had prognostic value in colon cancer." (PMID 34885003, 2021). "We also examined the protein and mRNA expression levels of the anti-colon cancer action pathway, SDF-1/CXCR4 axis before and after intervention with the ACE drug pair." (PMID 34531745, 2021). "Flow cytometric analysis of surface protein expression on CT-26 cells demonstrated clear-cut expression of CXCR2, CXCR3, CXCR4 and CXCR5, suggesting a potential role of CXC chemokines in colon cancer cell biology." (PMID 34115261, 2021). "Herein, it was found that the murine colon cancer cell line CT-26 expressed several of the pro-inflammatory chemokine receptors in the CXC chemokine family, including CXCR2, CXCR3 and CXCR4." (PMID 34115261, 2021). "In recent studies, we established that CXCR4 antagonist MSX-122 (substituted pyrimidine-2-amine) blocked CXCL12-induced EGFR transactivation and colon cancer progression in azoxymethane-induced mouse model." (PMID 34298991, 2021). "Human colon cancer tissue, spleen tissue and lymph node tissue were used as CXCL12 CXCR4 and CXCR7 positive control, respectively, the Goat‐isotype and rabbit isotype antibody were used as negative control for placenta tissues." (PMID 31991051, 2020). "For example, CD164 is highly expressed in colon cancer, where it promotes proliferation and metastasis by regulating signaling through the CXCL12 (SDF-1) receptor CXCR4." (PMID 31007847, 2019). "Accordingly, it has been reported that colon cancers and colon cancer cell lines also abundantly express MIF receptors CXCR2 and CXCR4." (PMID 31557914, 2019). "RT-PCR and western blot were detected the expression of CXCL12, CXCR4 and PTEN in colon cancer cells and stromal cells." (PMID 31500630, 2019).